DCLK1 (doublecortin like kinase 1)
Diseases named in the same sentence as DCLK1 in open-access papers (continued):
Sharing a sentence is not in itself a finding about the gene and the disease.
tumor (continued). "The addition of DCLK1 inhibitor DCLK1-IN-1 to the third-generation EGFR-TKI inhibitor Osimertinib resistant PDO downregulates the Wnt/β-catenin signaling pathway, restores tumor sensitivity to Osimertinib." (PMID 36696006, 2023). "In this study, we found that DCLK1 played a prominent role in maintaining CSC traits, promoting metastasis and reducing infiltration of CD8+ cells in tumor immune microenvironment with a concomitant resistance to chemotherapeutics and immune checkpoint inhibitors (ICIs) in TNBC." (PMID 37069669, 2023). "However, there may be DCLK1-dependent tumor-promoting mechanisms independent of its MT association." (PMID 36979969, 2023). "In addition, inhibition of DCLK1 kinase activity by DCLK1-IN-1 treatment reduced the PGE2 level in both plasma and tumor tissues in MC38 syngeneic mice." (PMID 35910805, 2022). "In addition, IHC analysis confirmed that DCLK1 inhibitor decreased the protein expression of DCLK1 and CCAR1 in subcutaneous tumour in both of DCLK1‐overexpressing and the control groups." (PMID 35522902, 2022). "Doublecortin-like kinase 1 (DCLK1), involved in the epithelial-mesenchymal transition (TME) and tumor progression, is a novel target for CRC immunotherapy and anti-DCLK1 CAR T-cells resulted in cytotoxicity and secretion of IFN-γ after incubation with CRC cells in two." (PMID 35814023, 2022). "Intravenous injections of DCLK1-directed CAR T-cells have been shown to reduce tumor size in tumor-bearing mice, strongly suggesting that DCLK1-based CAR T-cells inhibit CRC tumor growth in vivo without obvious cytotoxicity to normal tissues." (PMID 36458008, 2022). "Much of the initial research published by our and other groups have recently revealed the doublecortin-like kinase 1 (DCLK1) antigens as valuable predictive biomarkers and suitable candidates for tumor immunotherapy in terms of their role in regulating diverse tumorigenesis pathways." (PMID 35717205, 2022). "In addition, DCLK1 was shown to be overexpressed and deregulated in > 93% of RCC tumours, and its knockdown by siRNA in RCC cells resulted in decreased expression of EMT and cancer stem cell (CSC) markers." (PMID 34099013, 2021). "Despite these interesting findings, the influence of DCLK1 kinase inhibitors on anti-tumor immunity has not been previously assessed." (PMID 34830884, 2021). "Next, we investigated whether HNK affects CSCs by determining the expression of DCLK1 and LGR5 in tumor tissues." (PMID 34206989, 2021). "Given this background, we decided to investigate whether DCLK1 might also be related to tumor immune excluded/desert phenotype in the RCC microenvironment and whether DCLK1-IN-1 might be an effective therapy against this property." (PMID 34830884, 2021). "Both DCLK1 and LGR5 were highly increased in tumour tissue compared with the matched controls." (PMID 32814764, 2020). "We next analysed the mRNA expression levels in tumour and adjacent mucosa samples from 17 paired CRC patients, which also suggested a significantly positive correlation between GLI1 and the stemness markers DCLK1 and LGR5 with elevated expression of all three genes in tumour tissues." (PMID 32814764, 2020). "In tumours of mice treated with gemcitabine alone, expression of the stem cell marker DCLK1 was elevated (although not reaching statistical significance)." (PMID 32203220, 2020). "Importantly, our findings demonstrate for the first time that DCLK1 directly activates RAS and that DCLK1-targeted monoclonal antibodies can be used to inhibit PDAC tumor growth in xenografts and the KPC mouse model." (PMID 31467540, 2019). "Interestingly and importantly, in LGR5+ or DCLK1+ cells of established colorectal tumors, HES1 deletion induced immediate apoptosis, thus consistently reducing the tumor burden." (PMID 29652830, 2018). "However, recently Nakanishi and coworkers reported the identification of doublecortin-like kinase 1 (DCLK1) as a marker allowing us to distinguish between normal and tumor colon stem cells." (PMID 29652830, 2018).
tumor (continued). "In addition, DCLK1 also regulates Notch-1 via a miR-144 dependent mechanism and its downstream effector HES1 to promote tumor xenograft growth." (PMID 29246000, 2017). "Immunohistochemistry of primary tumor sections for the stem cell marker (DCLK1) demonstrated that tumors from mice treated with gemcitabine alone, or in dual combinations with either AMG102 or compound-A exhibited higher expression of DCLK1." (PMID 29100344, 2017). "Of note, DCLK1 was found also to have independent favorable prognostic impact on DFS of IBC-NED (HR=0.288, p = 0.011, 95%CI= 0.111-0.748) after adjustment of grade, age, tumor size, LVI, pN stage, HER2, Ki67, PR and neuroendocrine markers expression." (PMID 26621833, 2016). "In the present study, licofelone+gefitinib suppressed DclK1 CSC marker and inhibited tumor progression, compared with individual drug treatments, suggesting that the combination may effectively act on eliminating CSCs." (PMID 26429877, 2015). "DCLK1 knockdown resulted in decreased expression of OCT4 (>30%), KLF4 (>45%), LIN28 (>40%), and NANOG (>50%) in tumor xenografts." (PMID 26468984, 2015). "In the present study, licofelone significantly suppressed increases in DclK1 along with other CSC markers (Lgr5, CD133 and CD44) in correlation with its inhibition of tumor progression, suggesting that licofelone may kill CSCs." (PMID 25906749, 2015). "Diffuse cytoplasmic expression of DCLK1 was observed in the tumor area, while no positive signal was visible in the surrounding non-tumorous tissue." (PMID 26622789, 2015). "Similarly to our previous studies, following the knockdown of DCLK1, we also observed inhibition of NOTCH1 via miR-144 in AsPC-1 tumor xenografts." (PMID 24040120, 2013). "Our data show a key role of DCL in NB tumor development and in energy supply of NB cells, a function that has not been reported for the DCLK1 gene or any other member of the DCX family." (PMID 24086625, 2013). "Mechanistically, DCLK1 bound and phosphorylated XRCC5, which in turn transcriptionally activated cyclooxygenase-2 expression and enhanced prostaglandin E2 production; these events collectively generated the inflammatory tumor microenvironment and enhanced the aggressive behavior of CRC cells." (PMID 35910805, 2022). "It is conceivable that one or more subsets of acinar cells might be endowed with superior tumor-initiation capacity; for example, FACS-sorted Doublecortin-like Kinase 1 (Dlck1)-expressing acinar cells (represent 0.1–0.5% of the exocrine pancreas) more potently generate duct-like spheres in vitro." (PMID 32932616, 2020). "Our data is consistent with these findings, as we could not detect Dclk1 and other markers of tuft cells in tumor samples and most of the metaplastic tuft-like cells did not contain mucins." (PMID 32908137, 2020). "Moreover, targeting DCLK1-mediated EMT to regulate TGF-β pathway may alter resistance to CTLs and other anti-tumor immune cells." (PMID 33348546, 2020). "The expression levels of DCLK1 in the tumor tissues did not predict survival (data not shown)." (PMID 31467540, 2019). "Importantly, the ablation of the cells marked by tumor stem cell marker DCLK1 resulted in tumor regression without substantial damage to normal intestinal tissue." (PMID 29652830, 2018). "Using lineage-tracing experiments, Nakanishi and coworkers provided evidence that DCLK1 does not mark intestinal stem cells in the normal intestine, but marks tumor-initiating cells, continuously producing a tumor cell progeny in the adenomatous polyps of SpcMin/+ mice." (PMID 29652830, 2018). "It is not clear whether the aberrant DCLK1 expression contributed to IBC tumor aggressiveness as in gastrointestinal cancers." (PMID 26621833, 2016).
tumor (continued). "Furthermore, miR-15b overexpression suppressed tumorigenic properties of tumour-initiating cells and restored sensitivity to adjuvant chemotherapy and neoadjuvant radiotherapy in CRC patients by targeting doublecortin-like kinase 1 (DCLK1), a putative gastrointestinal stem cell marker." (PMID 39456841, 2024). "Although bioinformatics analysis indicated a positive correlation between the mRNA expression of DCLK1 and YAP1 in tumor samples, there were no significant changes in the mRNA or protein expression levels of YAP1 in PCa cell lines after DCLK1 overexpression or knockdown at the cellular level." (PMID 39781521, 2025). "As the results showed, DCLK1 knockout resulted in a significant inhibitory effect on tumor growth in immunocompetent BALB/c mice, while in immunocompromised BALB/c nude mice, the difference between DCLK1-knockout tumors and the control group was not significant." (PMID 37069669, 2023). "However, we have shown that DCLK1 and LGR5 do not mark in HCT-116/OxR chemoresistant cells with or without OXA treatment in mice in tumor sections by immunochemical evaluation in this study." (PMID 27668882, 2016).
infection (16 papers, 2013 to 2025). The state of being infected such as from the introduction of a foreign agent such as serum, vaccine, antigenic substance or organism. "Elp3 deficiency impaired tuft cell amplification post-infection, as evidenced by anti-Dclk1 immunofluorescence (IF) analyses." (PMID 39085648, 2024). "In response to CR infection, increased DCLK1 expression was particularly noticeable with a decline in the CR+DBZ group." (PMID 40839695, 2025). "Infection with H. diminuta resulted in significant (p<0.05) ~12-fold and ~8-fold increases in jejunal doublecortin-like kinase-1+ (DCLK1+) epithelial tuft cells in BALB/c and C57BL/6 mice, respectively at 11 dpi." (PMID 39083533, 2024). "We found that early-life RV infection induced the appearance of DCLK1+ tuft cells and that heterologous infection with both RV1B and RV2 caused a further increase in DCLK1+ cells." (PMID 38061015, 2024). "BALB/c and C57BL/6 mice infected with H. diminuta expelled the worms by 11 days post-infection (dpi) and displayed DCLK1+ (doublecortin-like kinase 1) tuft cell hyperplasia in the small intestine (not the colon) at 11 dpi." (PMID 39083533, 2024). "Confocal staining of DCLK1 revealed an increase in the number of tuft cells at both day 6 and day 8 after infection when comparing DMH1-treated to DMSO-treated animals." (PMID 35559665, 2022). "We found upregulation of DCLK1 in the Butyrate vs. CR group and a decreased expression of DCLK1 after CR infection." (PMID 35008767, 2021). "During T. muris trickle infection there was a small but significant increase tuft cell numbers (identified by Dclk1 expression) in the caecum despite a significant decrease in ILC2s at this time point." (PMID 31730667, 2019). "Our next aim was to determine the mechanism behind the diminished DCLK1 positive tuft cells in i-Raptor−/− mice after Tm infection, specifically we wanted to explore the role of Raptor in tuft cell differentiation in the stem & transient amplifying cells." (PMID 28717211, 2017). "Importantly, Stat6 phosphorylation as well as Dclk1 induction were severely impaired in intestines from TgAtf4IEC mice 7 days post-infection, suggesting that tuft cell amplification was abolished upon Atf4 overexpression in vivo." (PMID 39085648, 2024). "Thus, we found significant interactions of diet and infection for several genes, especially those related to the mucosal barrier, such as DCLK1, HDAC9, IL13RA1, MUC2 and HDAC1 (Fold change 2.5, 1.9, 1.3, 1.3 and − 1.2, respectively)." (PMID 38081984, 2023). "Despite recent advances, many fundamental questions remain about the biology of the DCLK1 isoforms and whether Notch–DCLK1 axis regulates the mucosal immune responses to infection." (PMID 34226497, 2021). "In response to either CR infection or CR infection+vehicle treatment, staining for both CD44 and Dclk1 increased in the colonic crypts." (PMID 24278135, 2013). "In contrast, infection with H. diminuta did not result in a change in the number of DCLK1+ tuft cells in the colon of BALB/c or C57BL/6 mice, prompting a focus on small intestinal tuft cells in subsequent studies." (PMID 39083533, 2024). "However, infection of mice with RV2 one week after the previous RV1B infection further increased the number and percentage of airway DCLK1+ cells compared with RV1B alone." (PMID 38061015, 2024). "Immunofluorescent staining for the tuft cell marker Dclk1 revealed increased numbers of tuft cells in Gpr44−/− compared with WT mice, though only in the naive state, with no significant change in the infection-induced increase compared with WT mice." (PMID 34283207, 2021). "In the immune-competent Rag-1+/+ mice, however, we did not see any increase in DCLK1 levels in response to CR infection compared to uninfected controls (2.57 vs. 2.44%) (data not shown)." (PMID 34226497, 2021).
infection (continued). "In sharp contrast, the i-Raptor−/− mice did not respond to Tm infection as demonstrated by the lack of DCLK1 expression and IL-25 in epithelium and IL-13 in lamina propria." (PMID 28717211, 2017).
gastrointestinal tumors (7 papers, 2014 to 2025). "The epigenetic repression of the 5′(α)-promoter of DCLK1 during early colon carcinogenesis leads to the loss of DCLK1-L expression and a subsequent DCLK1-S expression activated by an alternate-(β) promoter within IntronV of the DCLK1 gene." (PMID 40839695, 2025). "Recently, DCLK1 has been reported as a CSC marker of gastrointestinal tumor and has gained increasing attention." (PMID 37069669, 2023).
adenocarcinoma (4 papers, 2013 to 2019). A common cancer characterized by the presence of malignant glandular cells. "To verify that the Dclk1 upregulation in tumors of Apc mutation with activated wnt, we did IHC for β-catenin and found that β-catenin was localized in the intestinal regions identified as high-grade dysplasia and adenocarcinoma, and most of them strongly stained in the nucleus." (PMID 25211188, 2014). "In addition, DCLK1 knockdown in APCmin/+ mice attenuates intestinal adenoma and adenocarcinoma, whereas DCLK1 overexpression facilitates intestinal tumorigenesis in this model." (PMID 28757546, 2017). "In support of these findings, knockdown of Dclk1 in elderly ApcMin/+ mice attenuates intestinal adenomas and adenocarcinoma by decreasing pluripotency, EMT and onco-miRNAs indicating that Dclk1 overexpression facilitates intestinal tumorigenesis." (PMID 25211188, 2014).
colon (3 papers, 2020 to 2025). "Although the underlying signaling mechanisms of DCLK1+ epithelial cell-mediated tumorigenesis require further elaboration, DCLK1 and DCLK1+ epithelial cells such as TCs are likely to be a target for new classes of immunotherapies and TME-remodeling drugs in gastrointestinal tract cancers." (PMID 33348546, 2020).
psychiatric disorder (3 papers, 2009 to 2016). A disorder characterized by behavioral and/or psychological abnormalities, often accompanied by physical symptoms. "In this study, we aimed to investigate the effect of genetic variants in DCLK1 on psychiatric disorders which have cognitive dysfunction as a strong phenotypic component." (PMID 22539971, 2012). "In this study we show that genetic variants in DCLK1 are associated across psychiatric disorders." (PMID 22539971, 2012).
cardiovascular diseases (2 papers, 2023 to 2025). "However, the specific role of doublecortin-like kinase 1 (Dclk1) in cardiovascular diseases is limited." (PMID 40332511, 2025).
bacterial infection (1 paper, 2021). "Since neutrophils besides providing a front line of defense against bacterial infection also act as mediators of inflammation, we next studied co-localization of NE with DCLK1 and Citrullinated-H3 (Cit-H3) to detect neutrophil extracellular trap (NET) formation in the FFPE sections." (PMID 34226497, 2021).
metabolic disorders (1 paper, 2025). "As a multifunctional protein kinase, DCLK1 not only participates in neuronal differentiation by regulating microtubule dynamics, but also plays an important role in metabolic disorders." (PMID 41463391, 2025).
neurodevelopmental disorder (1 paper, 2021). A behavioral and cognitive disorder with onset during the developmental period that involves impaired or aberrant development of intellectual, motor, or social functions. "DCX-inactivating mutations cause severe structural brain abnormalities, whereas the case for DCLK1 and DCLK2 as disease genes for neurodevelopmental disorders is currently circumstantial." (PMID 33199366, 2021).
DCLK1 also shares sentences with these, for which no sentence is quoted: glioblastoma (3 papers); bipolar affective disorder (2); diabetic retinopathy (2); esophageal squamous cell carcinoma (2); gastric adenocarcinoma (2); glioma (2); Parkinson disease (2); proliferative diabetic retinopathy (2); stomach cancer (2); acute myeloid leukemia (1); acute pancreatitis (1); acute respiratory distress syndrome (1); age-related hearing loss (1); autism (1); Canavan disease (1); carcinoid (1); Cerebral ischemia (1); Cholecystitis (1); chronic pancreatitis (1); colorectal (1); colorectal adenocarcinoma (1); deafness (1); diabetic neuropathy (1); enteroviral infections (1); head and neck squamous cell carcinoma (1); Hodgkins lymphoma (1); hypertrophic cardiomyopathy (1); hypertrophy (1); kidney diseases (1); lung squamous cell carcinoma (1).
A further 15 diseases each share a sentence with DCLK1 in 1 paper.